GARIN5A (golgi associated RAB2 interactor 5A)
Description:
RAB2B effector protein which promotes cytosolic DNA-induced innate immune responses. Regulates IFN responses against DNA viruses by regulating the CGAS-STING signaling axis.
Synonyms: FAM71E1; GARIL5
Tractability: No criterion of Open Targets' tractability assessment is met for any kind of drug.
Gene: Protein-coding gene on chromosome 19 (50,466,785 to 50,476,866, reverse strand). Ensembl gene ENSG00000142530.
Subcellular location: Golgi apparatus
Subcellular location (Human Protein Atlas): Nucleoli fibrillar center
Gene Ontology:
Biological process: defense response to virus; innate immune response; positive regulation of type I interferon production
Cellular component: Golgi apparatus
Genetic constraint (gnomAD): Loss-of-function variants: 15 observed, 15.35 expected, observed/expected ratio (o/e) 0.98, 90% interval 0.65 to 1.5. The upper end of that interval is the gene's LOEUF score, 1.5, which puts it in group 6 of 6, group 1 being the genes least tolerant of losing a copy. Missense variants: 366 observed, 321.87 expected, observed/expected ratio (o/e) 1.14, 90% interval 1.04 to 1.24. Synonymous variants: 169 observed, 137.03 expected, observed/expected ratio (o/e) 1.23, 90% interval 1.09 to 1.4.
Homologues: Orthologues: chimpanzee GARIN5A (98% identical), dog GARIN5A (57% identical), pig GARIN5A (56% identical), rat Garin5a (55% identical), mouse Garin5a (50% identical), macaque GARIN5A (43% identical). Paralogues in human: GARIN5B (28% identical), GARIN4 (26% identical), GARIN2 (25% identical), GARIN3 (24% identical), GARIN6 (24% identical), GARIN1A (20% identical), GARIN1B (20% identical).
Diseases named in the same sentence as GARIN5A in open-access papers:
GARIN5A is named in the same sentence as 4 diseases in open-access papers, as found by Europe PMC text mining. Sharing a sentence is not in itself a finding about the gene and the disease.
GARIN5A shares sentences with these, for which no sentence is quoted: Azoospermia (1 paper); breast carcinoma (1); lupus erythematosus (1); male infertility (1).